STMN1 (stathmin 1)
Diseases named in the same sentence as STMN1 in open-access papers (continued):
Sharing a sentence is not in itself a finding about the gene and the disease.
pancreatic cancer (6 papers, 2018 to 2024). "MAPK activity suppresses miR-193b, derepressing STMN1 in pancreatic cancer cells and thereby enabling proliferation." (PMID 38893174, 2024). "For example, the expression of stathmin 1 was negatively related to the degree of tumor differentiation, and a high level of stathmin 1 tended to indicate distant metastasis in pancreatic cancer." (PMID 37162289, 2023). "It was reported that STMN1 were higher levels in pancreatic cancer than in the corresponding normal tissues." (PMID 34253824, 2021). "Chil3 and Stmn1 have been reported in pancreatic cancer but not in AP." (PMID 36671463, 2022).
triple-negative breast carcinoma (6 papers, 2016 to 2024). An invasive breast carcinoma which is negative for expression of estrogen receptor (ER), progesterone receptor (PR), and human epidermal growth factor receptor 2 (HER2). "In a similar vein, Yaming Li and colleagues demonstrated that targeting STMN1 can mitigate chemotherapy resistance and metastasis in triple-negative breast cancer." (PMID 38317842, 2024). "It has been reported that miR-770 can suppress the chemo-resistance and metastasis of triple-negative breast cancer via direct targeting of STMN1." (PMID 30524203, 2018). "The newly identified miR-770/STMN1 axis provides novel insight into the chemo-resistance and metastasis of triple negative breast cancer, and represents a potential therapeutic target for the treatment of triple negative breast cancer." (PMID 29323124, 2018). "A recent study reported that miR-770-5p is downregulated in chemo-resistant triple negative breast cancer (TNBC) tissues while its ectopic expression antagonized resistance and metastases by targeting STMN1." (PMID 31009516, 2019).
acute leukemia (5 papers, 2015 to 2025). A clonal (malignant) hematopoietic disorder with an acute onset, affecting the bone marrow and the peripheral blood. "STMN1 is abundant in acute leukemia blasts and its expression was decreased when inducing differentiation by exposing an acute promyelocytic leukemia cell line HL60 to Me2SO or exposing erythroleukemia cells K562 to hemin." (PMID 33921319, 2021). "The relevance of Stathmin 1 in hematological malignancies has been well described in acute leukemia and lymphoma." (PMID 26356819, 2015). "Aberrant Stathmin 1 expression has been described in several hematological malignancies, including lymphomas, acute leukemias and myelodysplastic syndromes." (PMID 26356819, 2015). "STMN1 functions as a marker of normal and malignant hematopoietic cell proliferation, and it plays a key role in cell cycle progression and clonogenicity in acute leukemia cells." (PMID 36551566, 2022). "Among its components, stathmin 1 (STMN1) and ezrin (EZR) stand out for their significant involvement in the pathogenesis and progression of acute leukemias." (PMID 40982350, 2025). "This review aims to explore the roles of STMN1 and EZR in the pathogenesis of acute leukemias, assessing their potential as therapeutic targets." (PMID 40982350, 2025). "While some studies suggest that STMN1 expression does not affect the prognosis of patients with acute leukemias, other research has observed that high STMN1 expression negatively affects the survival of patients with AML." (PMID 40982350, 2025). "In this review, evidence on the involvement of stathmin 1 (STMN1), a key protein in the regulation of microtubule dynamics, and ezrin (EZR), the plasma membrane-microfilament linker, in the pathogenesis, progression, and response to therapy in acute leukemias is presented." (PMID 40982350, 2025).
esophageal squamous cell carcinoma (5 papers, 2012 to 2023). Esophageal squamous cell carcinoma (ESCC) is a type of esophageal carcinoma (EC) that can affect any part of the esophagus, but is usually located in the upper or middle third. "High level of STMN1 expression is associated with poor prognosis in various malignancies including breast cancer, prostate cancer, malignant mesothelioma, cervical cancer, and esophageal squamous cell carcinoma." (PMID 22470493, 2012). "The current study showed that STMN1 is a prognostic predictor of esophageal squamous cell carcinoma and a marker of PI3K pathway activation." (PMID 36127700, 2022). "Jiang found that STMN1 promotes the proliferation, migration, and invasion of esophageal squamous cell carcinoma by activating the PI3K pathway." (PMID 35126478, 2022).
lung adenocarcinoma (5 papers, 2017 to 2023). A carcinoma that arises from the lung and is characterized by the presence of malignant glandular epithelial cells. "Also, STMN1 expression was an independent prognostic factor in patients with early-stage lung adenocarcinoma but only in patients with early-stage cancer." (PMID 36127700, 2022).
prostate adenocarcinoma (5 papers, 2021 to 2025). "Importantly, we observed a significant increase in STMN1 expression in NEPC compared to prostate adenocarcinoma, suggesting its potential role as a diagnostic and prognostic marker for advanced PCa." (PMID 39711570, 2024). "In summary, our study highlights the increased expression of STMN1 in NEPC and proliferating prostate adenocarcinoma cells, indicating its potential utility as a diagnostic and prognostic marker for advanced PCa." (PMID 39711570, 2024). "Notably, STMN1 expression was significantly higher in NEPC compared to prostate adenocarcinoma, suggesting its role in NEPC progression." (PMID 39776361, 2025). "Additionally, elevated STMN1 expression was detected in proliferating prostate adenocarcinoma cells, where it correlated with higher tumor grades and worse clinical outcomes." (PMID 39776361, 2025). "Another study identified five glycolysis-related mRNAs (GYS2, STMN1, PPFIA4, KDELR3, and ABCB6) which were associated with patients experience biochemical recurrence (BCR) after radical prostatectomy (RP) in patients with prostate adenocarcinoma." (PMID 34489401, 2021). "While STMN1 expression has been noted in PIN and prostate adenocarcinoma (AdPC), its role in aggressive PCa forms like NEPC remains poorly defined." (PMID 39776361, 2025).
squamous cell carcinoma (5 papers, 2016 to 2024). A carcinoma arising from squamous epithelial cells. "It has been reported that the high STMN1 expression is closely associated with cancer progression and chemo-resistance in squamous cell carcinoma." (PMID 39689117, 2024). "Based on the RNA sequencing data in the Cancer Genome Atlas (TCGA), the mRNA expression of STMN1 was slightly higher in squamous cell carcinoma." (PMID 29577639, 2018).
glioblastoma (4 papers, 2016 to 2023). The most malignant astrocytic tumor (WHO grade IV). "ZYX acts as an oncogenic gene in glioblastoma multiforme cells, and higher ZYX expression promotes the metastasis of glioblastoma multiforme cells by regulating the transcription of STMN1." (PMID 37626810, 2023). "Many studies indicate that STMN1 expression is elevated in glioblastomas and a variety of human cancers." (PMID 36142793, 2022). "A strong correlation between MELK and STMN1 expressions was observed (r = 0.741, p < 0.0001) in glioblastoma (GBM) samples." (PMID 26973435, 2016).
B-cell lymphoma (3 papers, 2015 to 2023). "To date, a number of biomarkers with a diagnostic value for each B-cell lymphoma subtype have been determined: BCL2, BCL6, CD10, CD21, and STMN1 in FL; D1 and SOX11 in MCL; FOXP1 and MUM1 in ABC-DLBCL; CD10, BCL2, BCL6, LMO2, and GCET1 in GC-DLBCL; and CD30, CD15, EBV, BOB1, OCT2, and CD79a in HL." (PMID 37894763, 2023).
breast tumor (3 papers, 2023 to 2026). "STMN1 (Stathmin 1) is a microtubule‐binding protein associated with breast tumor progression and paclitaxel resistance." (PMID 41523581, 2026). "Stmn1 encodes stathmin 1, which has been identified as strongly associated with the cell cycle in macrophages from the lungs of mice with in situ breast tumours." (PMID 39129565, 2024).
Cognitive impairment (3 papers, 2013 to 2023). Abnormal cognition is characterized by deficits in thinking, reasoning, or remembering. "This suggests the presence of cognitive impairment in STMN1 KO mice, which contrasts with reports that STMN-deficient mice showed normal HIP-dependent spatial memory in a water maze." (PMID 31454951, 2019). "STMN1 KO mice tend to show subtle cognitive impairments that are only detectable using spontaneous behavior-driven tests." (PMID 31454951, 2019). "Therefore, the altered expression of both ARPC4 and STMN1 proteins in the hippocampus of our old samples let us hypothesize and confirm that a cognitive impairment may also occur in bovine during the physiologic aging." (PMID 37965495, 2023).
leiomyosarcoma (3 papers, 2022 to 2024). An uncommon, aggressive malignant smooth muscle neoplasm, usually occurring in post-menopausal women. "Consequently, STMN1 emerges as a remarkably sensitive indicator for leiomyosarcomas, albeit with limited specificity for diagnostic applications." (PMID 38818470, 2024). "In leiomyosarcoma, STMN1 has also been characterised by high expression and can be a sensitive biomarker with strong diagnostic efficacy." (PMID 34982796, 2022).
myelodysplastic syndrome (3 papers, 2015 to 2018). A clonal hematopoietic disorder characterized by dysplasia and ineffective hematopoiesis in one or more of the hematopoietic cell lines. "In malignant hematopoiesis, Stathmin 1 overexpression was reported in acute myeloid leukemia, acute lymphoid leukemia and myelodysplastic syndromes." (PMID 26356819, 2015).
myeloma (3 papers, 2022 to 2025). "In this context, 2 key myeloma markers, MYC and DKK1, as well as many other cancer-associated genes, including ADM, HDGF, IL15, HGF, STMN1, CDKN1B and CD82, were potentially regulated by the predicted ligands." (PMID 41056512, 2025). "In the recent study based on scRNA‐seq, STMN1 and TYMS were identified to be related to resistance pathways of myeloma cells." (PMID 35297204, 2022).
sarcoma (3 papers, 2012 to 2024). A usually aggressive malignant neoplasm of the soft tissue or bone. "STMN1 was shown to suppress mesenchymal cell motility and correlate with the metastatic phenotype in human sarcomas in vivo." (PMID 38893174, 2024).
schizophrenia (3 papers, 2012 to 2019). A major psychotic disorder characterized by abnormalities in the perception or expression of reality. "An increasing number of correlations are being reported between the STMN1 gene and a broad range of neuropsychiatric disorders such as schizophrenia and depression and attention-deficit/hyperactivity disorder." (PMID 31454951, 2019).
Sepsis (3 papers, 2023 to 2025). Sepsis is defined as life-threatening organ dysfunction caused by a dysregulated host response to infection. "Detection of STMN1+TUBA1B T cells may be able to predict recovery from sepsis." (PMID 38898888, 2024).
temporal lobe epilepsy (3 papers, 2013 to 2021). A localization-related (focal) form of epilepsy characterized by recurrent seizures that arise from foci within the temporal lobe, most commonly from its mesial aspect. "Interestingly, altered levels of STMN1 expression in human brain tissue has recently been linked to intractable temporal lobe epilepsy." (PMID 23840848, 2013). "For patients with intractable temporal lobe epilepsy, the expression of STMN1 was significantly decreased in the neuronal membrane and cytoplasm than in healthy controls." (PMID 33952343, 2021).
viral infection (3 papers, 2020 to 2024). "Existing studies have shown that STMN1 plays an important role in viruses infection, and low expression of STMN1 inhibits dengue viruses replication; In addition, miR-760-3p regulates decreased expression of MEF2B and CDC25B." (PMID 38178220, 2024).
acute myeloid leukemia (2 papers, 2017 to 2023). Acute myeloid leukemia (AML) is a group of neoplasms arising from precursor cells committed to the myeloid cell-line differentiation. "Acute myeloid leukemia (AML) is characterized by the overexpression of STMN1, which serves as a genetic marker for the disease." (PMID 38139868, 2023).
Alzheimer disease (2 papers, 2022 to 2024). A progressive, neurodegenerative disease characterized by loss of function and death of nerve cells in several areas of the brain leading to loss of cognitive function such as memory and language. "The genes brain expressed X‐Linked 1 (BEX1), brain expressed X‐Linked 3 (BEX3), and Stathmin 1 (STMN1) had been confirmed uniquely down‐regulated in excitatory‐ and inhibitory‐neuron in brain bearing AD according to single‐cell transcriptomic analysis of Alzheimer's disease." (PMID 38923860, 2024).
anemia (2 papers, 2015 to 2021). A reduction in the number of red blood cells, the amount of hemoglobin, and/or the volume of packed red blood cells. "The megaloblastic anemia and thrombocytosis phenotypes observed in aged Stmn1 knockout mice further support STMN1′s roles in hematopoiesis." (PMID 33921319, 2021). "In this study, we found that the Fanconi anemia protein, FANCC interacts directly with the microtubule-associated protein STMN1, involved in microtubule dynamics during cellular division." (PMID 26466335, 2015).
Cirrhosis (2 papers, 2021 to 2023). A chronic disorder of the liver in which liver tissue becomes scarred and is partially replaced by regenerative nodules and fibrotic tissue resulting in loss of liver function. "In addition, a slight increase of STMN1 mRNA was found in precancerous liver tissues (cirrhosis and dysplasia), suggesting that STMN1 may play an early role during hepatocarcinogenesis." (PMID 33922244, 2021).
dysplasia (2 papers, 2021 to 2024). A usually neoplastic transformation of the cell, associated with altered architectural tissue patterns. "The median STMN1 expression can be seen above the cut-off for CIN II in cases with a normal or LCIN dysplasia for non-pregnant WLWH while the median expression in cases with HCIN is below the cut-off for CIN II." (PMID 39508903, 2024).
esophageal adenocarcinoma (2 papers, 2021). A malignant tumor with glandular differentiation arising predominantly from Barrett mucosa in the lower third of the esophagus. "Overexpression of the somatic STMN1 Q18E mutation identified in esophageal adenocarcinoma promoted the malignant transformation of 3T3 fibroblast cells and chromosomal instability in K562 cells." (PMID 33921319, 2021). "A study found STMN1 expression acted as glycolysis-related gene signature and predicted prognosis of patients with esophageal adenocarcinoma." (PMID 34489401, 2021).
gastric adenocarcinoma (2 papers, 2012 to 2017). "Immunohistochemistry was performed to assess the STMN1 protein expression in 111 primary gastric adenocarcinoma samples." (PMID 22470493, 2012). "In conclusion, we demonstrated the up-regulation of STMN1 in gastric adenocarcinoma and the expression was correlated with poor disease-specific survival in diffuse type gastric cancer." (PMID 22470493, 2012). "In this study, we demonstrated the up-regulation of STMN1 expression in both mRNA and protein levels in gastric adenocarcinomas compared with normal gastric epithelium." (PMID 22470493, 2012). "In primary gastric adenocarcinoma, 28 of 50 cases (56%) showed more than 1.5-fold up-regulation of STMN1 mRNA expression in tumor tissue compared with the corresponding non-tumorous mucosa." (PMID 22470493, 2012). "Up-regulated STMN1 protein expression was observed in 4 out of 5 primary gastric adenocarcinomas comparing with the corresponding non-tumorous gastric mucosa." (PMID 22470493, 2012).
gastric tumor (2 papers, 2012 to 2016). "Frequent upregulation of STMN1 mRNA and protein in gastric tumors suggested a potential oncogenic role of this gene." (PMID 22470493, 2012).
lung squamous cell carcinoma (2 papers, 2022 to 2024). "Bao found that the increased expression of STMN1 is associated with the progression and chemoresistance of lung squamous cell carcinoma." (PMID 35126478, 2022). "Elevated STMN1 expression in lung squamous cell carcinoma correlates with vascular invasion, decreased sensitivity to paclitaxel, and unfavorable prognostic outcomes." (PMID 38317842, 2024).
medulloblastoma (2 papers, 2020). A malignant, invasive embryonal neoplasm arising from the cerebellum. "MiR-193a not only targeted MAX but several proliferation-related genes like CCND1, E2F1, STMN1, and chromatin modifier gene KMT2A that brought about widespread repression of gene expression in the MYC amplified Group 3 medulloblastoma cells." (PMID 32410663, 2020). "Thus, the downregulation of STMN1 and DCAF7 may contribute to the tumor-suppressive activity of miR-193a by decreasing proliferation, inducing apoptosis, and increasing radiation sensitivity of medulloblastoma cells." (PMID 32410663, 2020).
motor neuron diseases (2 papers, 2020 to 2021). "We have recently used this approach to identify alpha‐synuclein and stathmin 1 as phenotypic modifiers of pathology in motor neuron diseases." (PMID 32311115, 2020). "Transcriptomic studies have identified stathmin-1 (STMN1), a tubulin-depolymerizing protein, as a potential disease modifier in several motor neuron diseases, including SMA." (PMID 33996898, 2021).
oral squamous cell carcinoma (2 papers, 2012 to 2017). "Ueyama announced that high expression of STMN1 is a strong prognosis marker in oral squamous cell carcinoma patients treated by docetaxel-containing regimens." (PMID 29113350, 2017).
renal fibrosis (2 papers, 2020 to 2021). A final common manifestation of a wide variety of chronic kidney diseases characterized by glomerulosclerosis and tubulointerstitial fibrosis. "The same hypothesis applies to the decreased expression of STMN1, TMSB4X and MYH9 in HK-2 cells under diabetic-like conditions, because: i) STMN1 is a microtubule-destabilizing phosphoprotein whose deficiency in mice has been connected to the development of renal fibrosis." (PMID 32579601, 2020).
spinal muscular atrophy (2 papers, 2021 to 2022). A motor neuron disease that affect the muscles, and characterized by muscle weakness and atrophy resulting from progressive degeneration and irreversible loss of the anterior horn cells in the spinal cord (i.e., lower motor neurons) and the brain stem nuclei. "STMN1 has been shown to significantly reduce the SMA (spinal muscular atrophy) phenotype independent of restoring SMN protein." (PMID 33669581, 2021).
urothelial carcinoma (2 papers, 2016 to 2025). A malignant neoplasm derived from the transitional epithelium of the urinary tract (urinary bladder, ureter, urethra, or renal pelvis). "In contrast, STMN1 overexpression has been associated with poor survival as well as with local or distant metastasis formation in several types of human cancer, including bladder, breast, cervical, colorectal, gastric, head and neck, hepatocellular, ovarian, prostate and urothelial carcinomas." (PMID 26973435, 2016). "A biomarker panel comprising Stathmin-1, DJ-1/PARK7, Gamma-synuclein, and APOA4 reliably distinguished urothelial carcinoma from benign urothelium." (PMID 41357584, 2025).
acute renal failure (1 paper, 2015). "The AR-category derived from the Clontech Ab arrays and Gene Pattern analysis was particularly characterized by the downregulation of stathmin STMN1 and Stmn1 deficiency was shown to increase renal failure and delayed recovery from ischemia-reperfusion injury in homozygous knockout Stmn1 mice." (PMID 26962294, 2015). "Thus, the AR-signature expediently included major markers of acute renal failure (STMN1) as well as demonstrated alterations (NME1, Ras-Raf), which have been previously associated with the kidney transplantation specific treatments." (PMID 26962294, 2015).